BMP7 (bone morphogenetic protein 7)
Diseases named in the same sentence as BMP7 in open-access papers (continued):
Sharing a sentence is not in itself a finding about the gene and the disease.
glaucoma (2 papers, 2008 to 2025). Increased pressure in the eyeball due to obstruction of the outflow of aqueous humor. "Owing to its antagonistic relationship with TGF‐β, BMP‐7 has emerged as a promising therapeutic candidate, with the potential to alleviate fibrotic changes in the TM, restore normal aqueous humor outflow, and reduce the risk of glaucoma." (PMID 40496354, 2025). "We aimed to explore the potential of BMP‐7 as a treatment for steroid‐induced glaucoma by examining its ability to counteract the increase in TGF‐β2 induced by steroid treatment." (PMID 40496354, 2025). "Based on our finding that TGF‐β2 increases after steroid treatment and its known role in steroid‐induced glaucoma, we selected BMP‐7 as a candidate therapeutic antagonist." (PMID 40496354, 2025). "It is important to note that while BMP‐7 shows promise in preclinical studies, its efficacy and safety as a treatment for glaucoma, including steroid‐induced glaucoma, remain to be conclusively established in human clinical trials." (PMID 40496354, 2025). "BMP‐7 may serve as a promising therapeutic target for preventing or treating steroid‐induced glaucoma by maintaining normal aqueous humor outflow and preventing IOP elevation." (PMID 40496354, 2025). "In this study, we investigated the potential of BMP‐7 as a therapeutic agent to inhibit ECM accumulation, a key factor in the development of steroid‐induced glaucoma." (PMID 40496354, 2025). "BMP‐7 co‐treatment reduced ECM production and modulated ECM‐related gene expression, highlighting its potential as a therapeutic strategy to prevent steroid‐induced glaucoma." (PMID 40496354, 2025).
Granuloma (2 papers, 2013). A compact, organized collection of mature mononuclear phagocytes, which may be but is not necessarily accompanied by accessory features such as necrosis. "Interestingly, lack of BMP8a and BMP7 expression in Bmp8a−/− and Bmp8a/Bmp7−/− mice provoked inflammatory situations in the caput epididymides of these animals characterized by the occurrence of sperm-mediated granulomas." (PMID 23840489, 2013).
heart failure (2 papers, 2015 to 2021). Inability of the heart to pump blood at an adequate rate to meet tissue metabolic requirements. "Whilst BMP7 recombinant protein has shown beneficial effects in the prevention of fibrosis in heart failure in preclinical mouse models, the cost of ongoing administration of recombinant BMP7 protein to HF patients is a major issue that hinders its progression for therapeutic application." (PMID 33804032, 2021).
Hepatitis (2 papers, 2012 to 2024). Inflammation of the liver. "Gremlin expression did not correlate with the number of FGF-2 positive cells (r = 0.548, p = 0.191) or BMP-7 mRNA level (r = 0.051, p = 0.851) in the hepatitis group." (PMID 22839096, 2012).
Hydroureter (2 papers, 2012 to 2023). The distention of the ureter with urine. "Bmp7 deficiency caused renal dysplasia and hydroureter phenotype,while Bmp4 heterozygous mutants exhibit multiple defects in urinary system, which is similar with human congenital anomalies of the kidney and urinary tract CAKUT." (PMID 22485132, 2012). "Bmp7 deficient mice display a dysplastic kidney and hydroureter phenotype." (PMID 22485132, 2012).
invasive breast carcinoma (2 papers, 2016 to 2019). A carcinoma that infiltrates the breast parenchyma. "Similarly to BMP7, expression of BMP4 is low in invasive breast cancer and its signalling has been implicated in the maintenance of tumor dormancy." (PMID 27409832, 2016).
ischemic stroke (2 papers, 2013 to 2025). A stroke disorder caused by obstruction of blood flow to the brain, due to thrombotic (local blood clot formation) or embolic (due to a blood clot or other material traveling from another site) event. "The findings provide further insight into the mechanism by which BMP-7 exerts its neuroprotection and suggest that BMP-7 might be of therapeutic value for the treatment of ischemic stroke." (PMID 24287916, 2013).
kidney injury (2 papers, 2015 to 2018). Trauma to the kidney. "The results are consistent with a previous research demonstrating that Dex protected septic acute kidney injury through increasing BMP-7." (PMID 30618586, 2018). "In addition, Dex protects septic acute kidney injury through increasing BMP-7." (PMID 30618586, 2018). "Furthermore, Dex could protect septic acute kidney injury through increasing BMP-7." (PMID 30618586, 2018).
liver cancer (2 papers, 2014 to 2022). An epithelial or non-epithelial malignant neoplasm that arises from the liver. "Regarding liver diseases, while BMP7 has been proposed as a marker for hepatic carcinogenesis because its serum levels were found to be decreased in patients with liver cancer, other authors have reported that circulating BMP7 levels are augmented in patients with viral chronic liver diseases." (PMID 35614516, 2022).
liver disease (2 papers, 2017 to 2022). "One could hypothesize that the rise on BMP7 during liver disease is an adaptive response to liver damage and fibrosis, so that the increased BMP7 tries to counteract profibrotic effect of TGF-β in the fibrotic liver." (PMID 29295498, 2017).
lupus (2 papers, 2017 to 2023). "Already two decades ago, a study in two genetic models of chronic renal injury and fibrosis—mice deficient in the α3-chain of collagen IV, as well as MRL/MpJlpr/lpr lupus mice—demonstrated that treatment with recombinant human BMP-7 (rhBMP-7) improved renal function and survival." (PMID 37626268, 2023).
malignant glioma (2 papers, 1996 to 2021). A grade III or grade IV glioma arising from the central nervous system. "Our results showed a higher BMP7/pSmad5 level in human malignant glioma tissues compared to healthy brain tissues." (PMID 34357080, 2021). "Osteogenic protein (OP)-1/BMP-7, which is known to bind BMPR-IA, BMPR-IB and ActR-I, was expressed in nervous tissue and was also detected in anaplastic areas of malignant glioma." (PMID 8605097, 1996).
metastatic tumor (2 papers, 2014 to 2019). "A novel predicted pathogenic mutation in BMP7 was identified in the primary and metastatic tumor but the metastatic tumor had a unique copy neutral loss of heterozygosity event encompassing the entire chromosome arm 20 q including the BMP7 locus." (PMID 25315765, 2014).
neuropathies (2 papers, 2016 to 2020). "Studies show that overexpression of bone morphogenetic protein 7 (BMP7) is beneficial in both nerves and Schwann cells after sciatic nerve injury, and it improves neuropathy in rats." (PMID 32122297, 2020). "By showing that BMP7 is a negative regulator for peripheral myelination, our present study provides novel insights into developing therapeutic strategies for treating the PNS neuropathies." (PMID 27491681, 2016).
non-Hodgkin lymphoma (2 papers, 2012 to 2016). Distinct from Hodgkin lymphoma both morphologically and biologically, non-Hodgkin lymphoma (NHL) is characterized by the absence of Reed-Sternberg cells, can occur at any age, and usually presents as a localized or generalized lymphadenopathy associated with fever and weight loss. "In two-hundred and forty-four follicular lymphoma (FL) cases recognized during a population-based case-control study of non-Hodgkin lymphoma (NHL), five genes (GALNT12,BMP7, DUSP2,GADD45B, andADAM17) were found associated with the overall survival of FL and control of B-cell activity." (PMID 27322213, 2016).
obstructive uropathy (2 papers, 2023 to 2026). "Some trials show that BMP-7 could be used in the therapy of kidney diseases as recombinant BMP-7 infusions used in the pre-clinical phase decreased fibrosis and inflammation occurring in obstructive uropathy or slowed GFR decline in mice with lupus nephropathy." (PMID 37373629, 2023).
periodontal disease (2 papers, 2022 to 2024). "Among the top five hub genes highlighted in this interactome are IL17RC, CCN2, BMP7, TPM1, and TIMP1, all of which have been implicated in periodontal disease in conjunction with peri-implant disease." (PMID 39659491, 2024). "Our analysis revealed a co-expression network comprising 216 genes, including prominent hub genes such as IL17RC, CCN2, BMP7, TPM1, and TIMP1, which are implicated in periodontal disease." (PMID 39659491, 2024). "The study identified 216 genes, with top hub genes like IL17RC, CCN2, BMP7, TPM1, and TIMP1 involved in periodontal disease." (PMID 39659491, 2024).
pheochromocytoma (2 papers, 2015). "We previously reported that the BMP7 gene is overexpressed in pheochromocytomas (PCCs) developing in MENX-affected rats and human patients." (PMID 26337467, 2015).
prostate tumours (2 papers, 2013 to 2018). "The effect of BMP7 on cell survival has been studied essentially in prostatic tumors." (PMID 24069261, 2013).
psoriasis (2 papers, 2023 to 2025). An autoimmune condition characterized by red, well-delineated plaques with silvery scales that are usually on the extensor surfaces and scalp. "As tissue-resident immune sentinels, LCs are critical in the early pathogenesis of psoriasis, where activated keratinocytes in psoriatic lesions overproduce bone morphogenetic protein 7 (BMP7) to promote progenitor differentiation into proinflammatory LCs." (PMID 41009795, 2025). "In addition to strong BMP7 signaling, psoriatic lesional cells are marked by p38MAPK activation, and its activation in keratinocytes promotes psoriasis-like lesion formation in mice." (PMID 37539048, 2023).
renal carcinoma (2 papers, 2010 to 2014). A carcinoma arising from the epithelium of the renal parenchyma or the renal pelvis. "The same report further demonstrated that BMP-6, a close family member of BMP-7 inhibited human renal carcinoma cell line 112 in a dose dependent manner." (PMID 23675191, 2010).
renal dysplasia (2 papers, 2012 to 2021). Renal dysplasia is a form of renal malformation in which the kidney(s) are present but their development is abnormal and incomplete. "Recently, several genetic mutations, mainly associated with Six2, Wnt, Bmp7, and Hnf1β, and copy number variations have been identified in patients with renal dysplasia." (PMID 34395519, 2021).
Sepsis (2 papers, 2020 to 2025). Sepsis is defined as life-threatening organ dysfunction caused by a dysregulated host response to infection. "DEX reduces sepsis-induced AKI by decreasing TNF-α and MCP-1 and increasing BMP-7, which is associated with decreasing HDAC2 and HDAC5, as well as increasing acetyl histone H3." (PMID 40989844, 2025).
small cell lung carcinoma (2 papers, 2021 to 2022). Small cell lung cancer (SCLC) is a highly aggressive malignant neoplasm, accounting for 10-15% of lung cancer cases, characterized byrapid growth, and early metastasis. "Additionally, BMP7 was found to inhibit progression of small cell lung cancer by inducing cell cycle arrest." (PMID 34745928, 2021).
adrenocortical carcinoma (1 paper, 2020). "Notably, we next validated BMP7 and MAPK14 expression and SMAD1 activation in samples from patients with NSCLC and adrenocortical carcinoma that progressed in the lung after treatment with pembrolizumab and ipilimumab, respectively." (PMID 32973129, 2020).
allergic asthma (1 paper, 2014). A asthma with a basis in a pathological type I hypersensitivity reaction. "In conclusion, our work sheds light on the balance between TGF-β1 and BMP-7 in the remodeling process in the lung in a model of allergic asthma and proposes that the TGF-β1/BMP-7 ratio could be used as a marker of disease severity." (PMID 24781156, 2014).
Anorexia (1 paper, 2012). Lack of desire to eat (loss of appetite). "Initially, it was proposed that activation of mTOR signaling in the hypothalamus promoted anorexia; in fact it was demonstrated that short-term central administration of anorectic factors, such as leucine, leptin, CNTF, α-lipoic acid or BMP7 increase hypothalamic mTOR signaling." (PMID 23056530, 2012).
astrocytoma (1 paper, 2020). "From the 10 strongest associations, only TBPL1, MYPOP and BMP7 appeared to be differently expressed in astrocytoma, albeit not specific to only astrocytoma." (PMID 33057419, 2020).
autoimmune disease (1 paper, 2023). A disorder resulting from loss of function or tissue destruction of an organ or multiple organs, arising from humoral or cellular immune responses of the individual to their own tissue constituents. "Also, in the context of multiple sclerosis, relapsing patients exhibited overexpression of BMP-2,4,5 but not BMP-7, again suggesting a relative unavailability of BMP-7 in poorer autoimmune disease outcome." (PMID 37626268, 2023).
Barrett adenocarcinoma (1 paper, 2017). An adenocarcinoma arising from Barrett metaplastic epithelium in the esophagus. "Our findings are consistent with previous findings that BMP7 is shown to induce phosphorylation of Smad2/3 in Barrett’s adenocarcinoma cells and that BMP7 stimulates Smad3 target CAGA box promoter activity to a similar extent to that induced by TGF-β in a mammary epithelial cell line." (PMID 27696331, 2017). "In Barrett’s adenocarcinoma cells, Smad2/3 is phosphorylated in the presence of BMP7 and absence of TGF-β, but phosphorylation is inhibited with increasing concentrations of TGF-β." (PMID 27696331, 2017).
bladder cancer (1 paper, 2018). "Considering that BMP2 and BMP7 could promote the proliferation and migration of bladder cancer, we try to confirm whether BMP9 plays a role in the development of bladder cancer." (PMID 29642505, 2018).
bronchopulmonary dysplasia (1 paper, 2024). Bronchopulmonary dysplasia is a chronic respiratory disease that results from complications related to lung injury during the treatment of infant acute respiratory distress syndrome in low-birth-weight premature infants or from abnormal lung development in older infants. "On the other hand, BMP-7 is essential for developing alveoli in newborn rats with bronchopulmonary dysplasia." (PMID 39330747, 2024).
Cachexia (1 paper, 2023). Severe weight loss, wasting of muscle, loss of appetite, and general debility related to a chronic disease. "We found that there is a mild negative correlation between BMP7 expression (52% homology with gbb) and CHORDIN (CHRD, 40% homology with Sog) in cancers commonly associated with cachexia as well as non‐cachectic cancers, where the correlation is slightly strongly in the cachexia‐related cancers." (PMID 38014610, 2023).
cervical tumour (1 paper, 2020). "Previous studies have shown that BMP7 contributes to cervical tumour growth arrest and Wnt/β-catenin signalling activation is involved in the development and invasion of CSCC." (PMID 32041662, 2020).
chronic asthma (1 paper, 2014). An asthma that is characterized by the development of persistent airway inflammation and recurrent attacks of breathlessness and wheezing, which vary in severity and frequency. "When the TGF-β1/BMP-7 ratio was analyzed, acute asthma correlated with a low ratio whereas chronic asthma correlated with a higher ratio." (PMID 24781156, 2014). "The mRNA expression of these molecules, analyzed in homogenates of whole lung, showed similar levels of TGF-β1 in the acute and chronic asthma groups, but the expression of BMP-7 was much higher in the acute asthma group." (PMID 24781156, 2014).
Chronic colitis (1 paper, 2023). A chronic inflammatory disease of the large intestine (colon, cecum and rectum). "To date, there is insufficient information on the influence of BMP7 on the long bones, in particular the femur, in chronic colitis." (PMID 37626658, 2023). "Bone morphogenic protein 7 (BMP7) has a complex role in maintaining inflammation and bone remodeling but little is known about its anti-inflammatory potential in chronic colitis." (PMID 37626658, 2023).
chronic renal disease (1 paper, 2010). "BMP-7 also has positive effects on vascular calcification and bone disease associated with chronic kidney failure in animal models." (PMID 20698955, 2010). "Animal experiments have shown that administration of BMP-7 improves kidney recovery in models of acute and chronic renal disease." (PMID 20698955, 2010).
colorectal adenocarcinoma (1 paper, 2021). The most common type of colorectal carcinoma. "Furthermore, the human colorectal adenocarcinoma cell line, HT-29, was stimulated with TL1A, anti-TL1A antibody, or BMP-7 to assess EMT process." (PMID 34257516, 2021).
Corneal opacity (1 paper, 2018). A reduction of corneal clarity. "The results of this study demonstrate that delivery of BMP7+HGF genes into stromal fibroblasts/keratocytes via nanoparticle (PEI2-GNP) significantly reduced corneal opacity by 3 weeks post injury in a preclinical rabbit model of corneal fibrosis." (PMID 29490341, 2018).
deafness (1 paper, 2015). An inherited or acquired condition characterized by the complete loss of the ability to hear from one or both ears. "Heterozygous variations in BMP7 including a frame shift and missense mutation in individuals with a range of systemic abnormalities which included developmental delay, eye anomalies, deafness, scoliosis, and cleft palate further support that BMP7 gene is associated with NSOCs." (PMID 25662552, 2015).
diffuse midline glioma (1 paper, 2024). A diffuse glioma that arises from the midline structures of the central nervous system. "Combined tumor-autonomous BMP2/BMP7 expression drives a quiescent-invasive tumor cell state in pediatric diffuse midline gliomas (pDMG)." (PMID 39373720, 2024).
dry eye (1 paper, 2018). "The lacrimal lake, as observed on tear strips, appeared similar in both PEI2-GNP-naked vector and BMP7+HGF groups, suggesting that combination therapy with BMP7+HGF does not compromise tear production or invoke a dry eye condition." (PMID 29490341, 2018).
endometrial cancer (1 paper, 2022). Primary or metastatic malignant neoplasm involving the endometrium (mucous membrane that lines the endometrial cavity). "In contrast, TWSG1 suppresses BMP7-enhanced sphere formation and migration in endometrial cancer cells, indicating the tumor-suppressive role of TWSG1 in endometrial cancer." (PMID 36361543, 2022). "TWSG1 suppressed BMP7-enhanced sphere formation and migration in endometrial cancer cells, indicating its tumor-suppressive role." (PMID 36361543, 2022).
enthesitis (1 paper, 2016). Inflammation at the site of insertion of ligaments, tendons, and other fibrous structures into bone. "Expressions of further BMP family members (BMP-2, BMP-4, and BMP-7) were reportedly increased at sites of enthesitis in a mouse model of SpA and at the Achilles tendon in biopsies of early-stage humans enthesopathy." (PMID 27314037, 2016).
female infertility (1 paper, 2022). Diminished or absent ability of a female to achieve conception. "Our results suggest that aberrant KRAS/FOXO1/BMP7 signaling in theca cells is likely an important cause of anovulation and female infertility." (PMID 36060690, 2022).
fluorosis (1 paper, 2024). "The Col1a1, Bcl2, Fgfr1, Mmp9, Mmp13, Bmp2, and Bmp7 genes are the key regulatory factors in fluorosis bone metabolism." (PMID 39125380, 2024).
Gliosis (1 paper, 2017). Gliosis is the focal proliferation of glial cells in the central nervous system. "Gliosis resulting from BMP7 is mediated through an inflammatory response from retinal microglia." (PMID 28381236, 2017).
HCMV infection (1 paper, 2020). "In particular, HCMV infection led mainly to the over-expression of CCL2, CCL3, CCL11, CXCR4, IL-1β, IL13, MMP1, MMP3, MMP9 and MMP13, SERPINA1, TNFα, and BMP7, and the gradual and constant downregulation of IL13RA2 (up to almost 800-fold at 14 days p.i.)." (PMID 32899126, 2020).
hydronephrosis (1 paper, 2012). Collection of urine in the renal pelvis that results in dilatation of the renal pelvis and calyces. "In fact, expressions of Bmp signaling genes (e.g., BMP2, BMP7 and BMPRIA) are reported to be decreased in the fibrotic renal tissue of human hydronephrosis." (PMID 22860096, 2012).